KLF10 (KLF transcription factor 10)
Diseases named in the same sentence as KLF10 in open-access papers (continued):
Sharing a sentence is not in itself a finding about the gene and the disease.
cardiac hypertrophy (8 papers, 2018 to 2025). "Although KLF10 deficiency was initially reported to be involved in cardiac hypertrophy in 2007, they identified a functional role for KLF10 in myocardial infarction." (PMID 38279278, 2024). "Few male-specific leading genes appeared with significant fold changes, with the notable exception being transcription factor encoding Klf10, whose reduction is associated with cardiac hypertrophy." (PMID 37110207, 2023). "Recently, several studies reported that KLF10 KO (Knock out) is associated with defects in cell and organs such as osteopenia, abnormal tendon or cardiac hypertrophy." (PMID 29799499, 2018). "KLF10 KO male mice exhibited cardiac hypertrophy symptoms, such as elevated heart/body weight ratio, wall thickness, and ventricular size, compared to the control group." (PMID 38279278, 2024). "KLF10 is a hypertrophy suppressor that binds to the Pttg1 promoter as one of its target genes and plays a key role in cardiac hypertrophy expansion." (PMID 38279278, 2024). "KLF10 also complexed with pituitary tumor-transforming gene-1 (Pttg1), which is one of its target genes and plays an important role in cardiac hypertrophy." (PMID 29799499, 2018). "In another study, male KLF10 knock out mice developed cardiac hypertrophy compared to wild type mice." (PMID 29970016, 2018). "KLF10 has the potential for use as a marker for various diseases including diabetes, cardiac hypertrophy, and osteoporosis." (PMID 29799499, 2018). "By binding to Sp-1-GC rich DNA sequences, KLF10 regulates gene transcription and impacts multiple pathways of the physiological and pathological processes, including bone metabolism 5, cardiac hypertrophy 6, neovascularization 7, T cell differentiation 8,9, as well as tumorigenesis." (PMID 32549754, 2020). "PTTG1 was a potential target of KLF10 in cardiac hypertrophy 6,21 but their relationship in MM remains unclear." (PMID 32549754, 2020). "Of these only KLF4, KLF5, KLF10, KLF11 and KLF15 have been studied in cardiac hypertrophy." (PMID 29970016, 2018).
Obesity (8 papers, 2013 to 2025). Accumulation of substantial excess body fat. "In CD4+-T-cell-specific KLF10 knockout mice, a predisposition to obesity, insulin resistance, and fatty liver was observed, attributed to impaired CD4+ Treg mobilization to liver and adipose tissues and reduced TGF-β3 release." (PMID 38279278, 2024). "CD4+ T cell-specific KLF10 deficiency leads to inflammation in adipose tissue, IR, obesity and the onset of NAFLD with impaired Treg accumulation." (PMID 35912096, 2022). "TGFβ3 secretion was also found to be decreased in a genetic model of mice with CD4+ T cell-specific KLF10 knockout in vitro and in vivo, and these mice have a predisposition to obesity, insulin resistance, and fatty liver." (PMID 36425072, 2022). "However, adoptive transfer of Tregs in CD4+ T cell-specific KLF10 deficient mice impede obesity, IR, adipose tissue inflammation and fatty liver phenotype." (PMID 35912096, 2022). "Klf10, also known as TGFβ‐inducible early gene‐1 is a transcription factor, was recently identified as an important regulator of obesity and insulin resistance and acts as a downstream effector of exercise to combat nonalcoholic steatohepatitis." (PMID 39821584, 2025). "This study underscores that CD4+ T-cell KLF10 is a key regulator of obesity and insulin resistance by modulating Treg metabolism and mobilization." (PMID 38279278, 2024). "More recently, Klf10 has been described to be protective against oral cancer and has been implicated in immune CD4+ T-cell localization in tissues, leading to obesity, insulin resistance, and fatty liver development." (PMID 35736488, 2022). "Interestingly, KLF10 KO mice develop alterations in glucose metabolism in a sex-dependent manner, with hyperglycemia in males and obesity in females, reassembling the metabolic disorders observed in Firoc mice." (PMID 35563069, 2022).
liver fibrosis (7 papers, 2014 to 2024). "Our identification of ATF3 as a potential KLF10 target provides valuable insights into the molecular mechanisms underlying the protective role of KLF10 against liver fibrosis." (PMID 37628783, 2023). "Based on these findings, we aimed to identify potential target molecules involved in liver fibrosis and investigate the mechanisms underlying the KLF10 modulation of hepatic stellate cell activation." (PMID 37628783, 2023). "In this study, we aimed to identify potential target molecules during liver fibrosis to investigate the mechanisms underlying KLF10 modulation of HSC activation." (PMID 37628783, 2023). "Since KLF10 deficiency was associated with increased liver injury, we then evaluated the hepatic fibrosis." (PMID 32699233, 2020). "Since our study demonstrated that increased KLF10 coincided with progression of liver fibrosis, we evaluated if KLF10 expression was associated with HSC activation." (PMID 24986741, 2014). "Further studies should be warranted to assess the specific role and mechanism of KLF10 in NASH associated liver fibrosis." (PMID 24986741, 2014). "Further studies should elucidate the mechanisms underlying the action of KLF10 in liver fibrosis." (PMID 38279278, 2024). "Overall, our study provides novel insights into the molecular mechanisms underlying the protective effects of KLF10 in liver fibrosis, which could potentially guide the development of innovative therapeutic strategies for liver diseases." (PMID 37628783, 2023). "However, the results of our study regarding the effect of KLF10 loss on liver fibrosis and HCC development should be validated by different fibrosis and HCC models because some etiologies of chronic liver disease are more likely to induce liver fibrosis and HCC in clinical settings." (PMID 37946098, 2023). "Hepatic fibrosis was observed in sucrose diet-fed KLF10 KO mice due to ER stress, inflammation, and TGF-β-dependent SMAD3 signaling activation." (PMID 38279278, 2024). "In our previous study, we investigated the effects of KLF10 knockout (KO) in mice fed a high-sucrose diet (HSD) and observed an increased susceptibility to liver fibrosis." (PMID 37628783, 2023). "Our previous study demonstrated that KLF10 knockout mice develop severe liver fibrosis when fed a high-sucrose diet." (PMID 37628783, 2023). "The identification of KLF10 as a negative regulator of the TGF-β signaling pathway provides a basis for the development of novel therapeutic strategies for liver fibrosis." (PMID 37628783, 2023). "By RNA sequencing analysis of liver tissues from KLF10 knockout mice with severe liver fibrosis induced by a high-sucrose diet, we identified ATF3 as a potential target gene regulated by KLF10." (PMID 37628783, 2023). "With respect to liver fibrosis, we previously reported that high-fat diet (HFD)-induced liver fibrosis was accompanied by increased KLF10 expression." (PMID 37946098, 2023). "In KLF10 KO mice subjected to HSD or methionine- and choline-deficient diets feeding, liver fibrosis is associated with increased liver injury and hepatocyte death." (PMID 37628783, 2023). "We identified ATF3 as a potential target gene of KLF10 by RNA sequencing analysis of liver tissues from KLF10 KO mice with HSD-induced liver fibrosis." (PMID 37628783, 2023). "To identify potential mediators of KLF10 during liver fibrosis, we performed RNA sequencing on liver tissues from wildtype (WT) and KLF10 KO mice treated with the control diet or HSD." (PMID 37628783, 2023). "The increased liver inflammation and cell death in HSD-fed Klf10 KO mice motivated us to evaluate liver fibrosis." (PMID 33396939, 2020). "The current study suggests that KLF10 plays a protective role against the progression of hepatic steatosis into liver fibrosis in a lipogenic state." (PMID 33396939, 2020).
liver fibrosis (continued). "Klf10 KO mice developed hepatic fibrosis due to the induction of ER stress, inflammation, and Smad3 signaling in a lipogenic condition induced by a high-sucrose diet (HSD)." (PMID 33396939, 2020). "Depression of ChREBP coincided with increase of KLF10 expression that correlated with enhanced TGFβ and Col1α(I) mRNA expression that are signs of progressive liver fibrosis." (PMID 24986741, 2014). "In addition, KLF10 expression is significantly reduced in clock-deficient Bmal1 KO mice, suggesting that Bmal1 is an upstream positive regulator of KLF10 during liver fibrosis." (PMID 38279278, 2024). "In the present study, we investigated whether KLF10 plays an important role in generation of liver fibrosis using KLF10-deleted transgenic mice and examined the impact of KLF10 deletion in HCC development." (PMID 37946098, 2023). "Here, we investigated whether KLF10 deletion affects the development of liver fibrosis and hepatocellular carcinoma (HCC)." (PMID 37946098, 2023). "Liver fibrosis is commonly associated with TGF-β signaling, and our previous study demonstrated elevated expression of TGF-β/SMAD signaling components in the liver of KLF10 KO mice fed an HSD, which promotes liver fibrosis." (PMID 37628783, 2023). "Additionally, we have shown that HFD-induced liver fibrosis is accompanied by increased KLF10 expression." (PMID 37946098, 2023). "Another study showed that KLF10 depletion from hepatocytes leads to severe liver injury and progression to hepatic fibrosis in response to a high-sugar diet, suggesting defects in lipid metabolism in these mice could contribute to fibrosis." (PMID 36902112, 2023). "Conversely, KLF10 suppresses hepatic fibrosis by negating TGF-β signaling." (PMID 36902112, 2023). "Therefore, we investigated how KLF10 deletion affected TGFβ signaling and liver fibrosis in mice with HFD-induced chronic liver inflammation." (PMID 37946098, 2023). "Collectively, these data suggest that KLF10 may be a potential biomarker of hepatic fibrosis progression in NAFLD or other types of chronic liver disease." (PMID 33396939, 2020). "Although previous studies report that TGFβ plays an important role in progression of nonalcoholic steatohepatitis (NASH) by regulating liver fibrosis, the association of KLF10 and NASH has never been explored." (PMID 24986741, 2014). "In addition, KLF10 deletion activates HSCs, thus aggravating liver fibrosis." (PMID 38279278, 2024). "Therefore, we hypothesized that modulation of KLF10 expression would alter the extent of liver fibrosis in a HFD-induced fatty liver mice model." (PMID 37946098, 2023). "Regarding the specific mechanisms of the KLF10-ATF3 axis, it is important to note that our study focused on establishing the relationship between KLF10 and ATF3 in the context of liver fibrosis." (PMID 37628783, 2023). "KLF10 deletion resulted in an increased DEN-induced HCC burden with significant upregulation of SMAD2, although loss of KLF10 did not alter HFD-induced liver fibrosis." (PMID 37946098, 2023). "The HFD increased liver fibrosis, as evaluated by Sirius red staining, as well as the mRNA expression level of Col1α in the livers of KLF10 WT and KO mice, without significant differences between groups." (PMID 37946098, 2023). "Unexpectedly, HFD challenge did not lead to worsening of liver fibrosis in KLF10 KO mice compared with WT mice." (PMID 37946098, 2023). "Since our observations suggested that KLF10 expression increased with progression of NASH fibrosis and repressed as fibrosis regressed, in vitro study using primarily cultured hepatic stellate cells (HSCs), key players of liver fibrosis, was done." (PMID 24986741, 2014). "The lack of a significant difference in SMAD3 expression after DEN treatment in WT and KO mice may partially explain the absence of changes in liver fibrosis after KLF10 deletion." (PMID 37946098, 2023).
liver fibrosis (continued). "This study showed that KLF10 deletion resulted in an increased incidence of DEN-induced HCC in mice, without the onset of liver fibrosis." (PMID 37946098, 2023).
osteoporosis (7 papers, 2018 to 2025). A condition of reduced bone mass, with decreased cortical thickness and a decrease in the number and size of the trabeculae of cancellous bone (but normal chemical composition), resulting in increased fracture incidence. "In addition, KLF10 is identified in clinical studies as a gene whose altered expression levels or allelic variations are linked to decreased bone mass and osteoporosis." (PMID 35730406, 2022). "Mutations in the Klf10 gene, and altered expression levels of Klf10, have also been observed in human diseases such as osteoporosis and hypertrophic cardiomyopathy." (PMID 36507464, 2022). "However, it is not feasible to translate this to a human model, because the knockout of KLF10 may affect several human diseases such as cancer, cardiovascular disease, and osteoporosis." (PMID 35565995, 2022).
Hepatic steatosis (6 papers, 2014 to 2024). Steatosis is a term used to denote lipid accumulation within hepatocytes. "In addition, our data demonstrates that loss of KLF10 is associated with higher liver injury despite hepatic steatosis and inflammation similar to that seen in WT mice upon MCDD challenge." (PMID 32699233, 2020). "We also show that glucose and fructose induce Klf10, which helps mitigate glucose intolerance and hepatic steatosis in mice challenged with a sugar beverage." (PMID 34402428, 2021). "HFD resulted in slight hepatic lipid accumulation and led to hepatic steatosis in wild-type mice; however, liver damage was aggravated in KLF10-knockout mice, which exhibited an accumulation of lipid droplets and degeneration of ballooning in the liver." (PMID 34869587, 2021). "In conclusion, this study demonstrated that KLF10 is required for the protection against the progression of hepatic steatosis to NASH with fibrosis upon HSD." (PMID 33396939, 2020). "ChREBP, which is also suspected to be modulated by KLF10, is a transcription factor that is observed to play a protective role in insulin resistance although it would aggravate simple hepatic steatosis." (PMID 24986741, 2014). "In addition, KLF10 expression in primary hepatocytes was increased in response to PPARα activation, which promotes FA oxidation, indicating that KLF10 has a protective role in hepatic steatosis." (PMID 34869587, 2021). "Triglyceride and cholesterol concentrations as well as plasma ALT and AST levels were elevated in the KLF10 KO mice liver, whereas WT mice had minor hepatic steatosis but no apparent liver damage." (PMID 38279278, 2024). "Interestingly, hepatic steatosis and fibrosis observed in HSD-fed Klf10 KO mice were also reported in Mttp KO mice." (PMID 33396939, 2020). "Klf10 KO mice exhibited significant hepatic steatosis, inflammation, and liver injury upon HSD feeding, whereas the WT mice exhibited mild hepatic steatosis with no apparent liver injury." (PMID 33396939, 2020).
Hyperglycemia (6 papers, 2016 to 2026). An increased concentration of glucose in the blood. "KLF10-deficient mice also showed hyperglycemia in males and hypertriglyceridemia in females." (PMID 27899146, 2016). "In this study, we identify Krüppel-like factor 10 (KLF10) as a critical transcriptional mediator linking hyperglycemia to ferroptotic activation in VSMCs." (PMID 41926082, 2026). "Recently, activation of KDM6A-KLF10 positive feedback loop by hyperglycemia has also been reported to contribute to podocyte dysfunction through decreased nephrin expression by direct binding of KLF10 to the gene promoter together with the recruitment of DNMT1." (PMID 34630127, 2021). "A recent study by Lin and colleagues demonstrated that hyperglycemia amplifies a positive feedback loop between KLF10 and KDM6A and discovered that KLF10 recruits DNMT1 to the nephrin promoter, thus inhibiting its expression." (PMID 39595187, 2024).
Insulin resistance (6 papers, 2014 to 2025). Increased resistance towards insulin, that is, diminished effectiveness of insulin in reducing blood glucose levels. "We also observed that this up-regulation of KLF10 was accompanied by increased TGFβ signaling genes and suppressed ChREBP expression which was known to improve insulin resistance." (PMID 24986741, 2014). "Up-regulation of KLF10 was accompanied by suppressed carbohydrate response element-binding protein (ChREBP) that is known to be protective against insulin resistance." (PMID 24986741, 2014). "It is suggested that knockdown of KLF10 in insulin resistance could promote osteoblast differentiation." (PMID 35730406, 2022). "It is indicated that knockdown of KLF10 in insulin resistance may promote osteoblast differentiation and bone healing." (PMID 35730406, 2022). "Knockdown of KLF10 in insulin resistance could promote osteoblast differentiation and dental implant osseointegration in diabetic patients." (PMID 35730406, 2022). "It is assumed that knockdown of KLF10 in insulin resistance may promote osteoblasts differentiation and dental implant osseointegration in diabetic patients." (PMID 35730406, 2022). "It is assumed that knockdown of KLF10 in insulin resistance may promote osteoblast differentiation and bone healing." (PMID 35730406, 2022).
lung carcinoma (6 papers, 2016 to 2024). "The role of KLF10 in suppressing TGF-β-induced EMT was reported in lung cancer, demonstrating that KLF10 functions as a transcriptional repressor, particularly of the EMT-promoting transcription factor SLUG/SNAI2, thereby limiting the ability of TGF-β to induce EMT." (PMID 38279278, 2024). "Our analysis shows that KLF10 overexpression in HNSCC correlates with an unfavorable prognosis, as in lung cancer." (PMID 34830760, 2021).
bladder cancer (5 papers, 2020 to 2024). "It is verified that circFUT8 plays an inhibitory role in bladder cancer cells by targeting miRNA-570-3p/KLF10." (PMID 34178035, 2021). "The upregulation of linc00641 suppressed the proliferation, migration and invasion of bladder cancer cells and blocked tumor growth in vivo by interacting with miR-197-3p and targeting KLF10, leading to the inactivation of the PTEN/PI3K/Akt pathway." (PMID 33714199, 2021). "For example, linc00641 inhibited bladder cancer progression by targeting the miR-197-3p/KLF10/PTEN/PI3K/Akt cascade." (PMID 33714199, 2021). "LINC00641/miR-197-3p/KLF10/PTEN/PI3K/AKT cascade may be a promising target for bladder cancer treatment." (PMID 35155216, 2021). "However, it was shown that LINC00641 is a tumor suppressor in bladder cancer, as up-regulation of LINC0064 inhibited the progression of bladder cancer via the miR-197-3p/KLF10/PTEN/PI3K/AKT signal pathways." (PMID 32917936, 2020). "Only one study has reported that LINC00641 expression was down-regulated in bladder cancer, and it could suppress the progression of bladder cancer via the miR-197-3p/KLF10/PTEN/PI3K/AKT pathway." (PMID 32917936, 2020). "In conclusion, LINC00641 can competitively bind to miR-197-3p through the ceRNA mechanism to increase the expression of KLF10, further inhibit the activation of PTEN/PI3K/AKT pathway, and inhibit the proliferation, migration and invasion of bladder cancer cells." (PMID 35155216, 2021).